REST (RE1 silencing transcription factor)
Diseases named in the same sentence as REST in open-access papers (continued):
Sharing a sentence is not in itself a finding about the gene and the disease.
glioma (continued). "Hence, the objectives of this study are to investigate the clinical significance of REST, HAR1A, and HAR1B expression in pediatric and adult gliomas and their functional roles in key cancer hallmarks (including cell survival, proliferation and migration)." (PMID 39602392, 2024). "We discovered distinct DNA methylation patterns between pilocytic astrocytoma and the other cancer types in agreement with the opposite oncogenic and tumour suppressive role of REST in glioma and non-brain tumours." (PMID 37301955, 2023). "Based on the existing research and our findings, we infer that HDAC1/REST interaction may participate in glioma and the mechanisms of miR-9-5p and miR-105-5p/HDAC1/REST axis in glioma are needed to be validated." (PMID 36810892, 2023). "Moreover, higher REST expression was also significantly related with worse OS, PFI, and DSS in glioma patients, and was a weak independent prognostic factor (p = 0.051)." (PMID 34859007, 2021). "While in brain tissues, REST was found to bind tightly to Chr19 in both non-gliomas brain and two gliomas tissues, but moderately bound to Chr1 in non-cancerous brain and almost no binding to Chr1 in gliomas." (PMID 24391856, 2013). "This could explain the seemingly opposite effects of REST: REST is a negative prognostic factor in G2/G3 gliomas, and a positive factor in G4 gliomas." (PMID 38711090, 2024). "In conclusion, our results suggest that REST overexpression can reverse the inhibitory effects of erianin, and conversely, REST knockdown enhances the inhibitory effects of erianin, indicating that REST is the target of erianin in regulating gliomas and TMZ-resistant gliomas." (PMID 39039049, 2024). "In the present study, we assessed whether repressing and activating functions of REST are modified by the IDH-related phenotype in gliomas and U-87 MG glioma cell lines, the only established glioma cell line present as an isogenic pair differing just in the IDH1 status." (PMID 38711090, 2024). "Our results first suggested that REST expression was significantly positively correlated with immune cells, including B cells, CD8+ T cells, CD4+ immune cells, macrophages, neutrophils, and dendritic cells in glioma, as well as the particular biomarkers of these immune cells." (PMID 36810892, 2023). "However, comprehensive research on the expression, prognosis, and mechanism of REST in glioma remains absent." (PMID 36810892, 2023). "However, mRNA levels of RE-1 silencing transcription factor, REST, which has been proposed as a transcriptional regulator of tph2 through bipartite neuron-restrictive silencing element in glioma cells was not altered." (PMID 24416346, 2014). "Taken together, these results suggest that HAR1A and REST are negatively correlated in all glioma subtypes analyzed, and that the expression of these molecules is of prognostic relevance in adult lower grade gliomas, but not in the most aggressive gliomas (DIPG and GBM)." (PMID 39602392, 2024). "The identified gene regulatory networks and putative REST cooperativity with other TFs, such as KAISO, show distinct REST target regulatory networks in IDH-WT and IDH-MUT gliomas, without concomitant DNA methylation changes." (PMID 38711090, 2024). "We found that HAR1A and HAR1B have a significant positive correlation in both datasets, HAR1A and REST have a significant negative correlation in both datasets, and HAR1B and REST have a significant negative correlation in lower grade gliomas, but unexpectedly, do not correlate in the GBM dataset." (PMID 39602392, 2024).
medulloblastoma (25 papers, 2012 to 2025). A malignant, invasive embryonal neoplasm arising from the cerebellum. "High levels of REST are a poor diagnostic indicator for medulloblastoma patients, while SAHA causes its decline and REST-dependent repression of cell growth." (PMID 34066495, 2021). "Elevated REST expression in medulloblastoma has been associated with tumor progression nevertheless, the tumor shows high sensitivity to HDAC inhibitors (HDACi)." (PMID 32720471, 2020). "The upregulation of REST in medulloblastoma is attributed to the increased secretion of proangiogenic transcription factor E26 oncogene homolog 1, and its target gene encoding the vascular endothelial growth factor receptor-1 (VEGFR-1)." (PMID 40006989, 2025). "Both REST and Myc oncogenes are found to be elevated in medulloblastoma by blocking neuronal differentiation and maintaining the “stemness” of these cells." (PMID 40006989, 2025). "Here, we demonstrate that REST promotes autophagy, a pathway that is found to be significantly enriched in human medulloblastoma tumors relative to normal cerebella." (PMID 38866867, 2024). "Human SHH-medulloblastoma tumors with higher REST expression exhibit nuclear localization of HIF1α, in contrast to its cytoplasmic localization in low-REST tumors." (PMID 38866867, 2024). "REST acts as a tumor suppressor in epithelial cancers and as an oncogene in childhood brain neoplasms such as neuroblastoma and medulloblastoma." (PMID 38711090, 2024). "The RE1 silencing transcription factor (REST) is a driver of sonic hedgehog (SHH) medulloblastoma genesis." (PMID 38866867, 2024). "The abnormal expression of REST in NSCs blocks their differentiation and promotes medulloblastoma formation." (PMID 37892159, 2023). "In medulloblastoma, REST promotes cancer progression via epigenetic modification and AKT activation." (PMID 37892159, 2023). "We had previously shown that REST expression is elevated in subgroups of patients with sonic hedgehog (SHH) medulloblastoma (MB)." (PMID 35600406, 2022). "Although REST is downregulated in most differentiated neurons, it is aberrantly upregulated in undifferentiated pediatric medulloblastoma." (PMID 34758854, 2021). "These indicate that REST can be used as a drug target and a new prognostic factor for medulloblastoma." (PMID 33834072, 2021). "Expression of the RE1‐silencing transcription factor (REST), a master regulator of neurogenesis, is elevated in medulloblastoma (MB) tumors." (PMID 33469989, 2021). "In this study, we used the GEO‐NCBI gene profiling data of tissue samples from medulloblastoma patients to explore the difference in the expression of REST between the medulloblastoma subgroups." (PMID 32720471, 2020). "The expression of the analyzed RE1‐containing REST target genes was overall reduced in medulloblastoma as compared to normal cerebellum tissue specimens." (PMID 32720471, 2020). "This study investigated the role of REST (DNA binding protein) in the anti‐cancer effects of histone deacetylase inhibitors (HDACi) in a medulloblastoma cell line." (PMID 32720471, 2020). "Several former studies used knockdown approaches in their analysis and they suggested REST as a key contributor in tumor cell growth and apoptosis and recommended REST as a promising target for medulloblastoma treatment." (PMID 32720471, 2020). "The results of this study showed that the expression of REST is elevated in most medulloblastoma subgroups compared to the non‐cancerous cerebellum." (PMID 32720471, 2020). "In this study, the expression of REST was evaluated across the medulloblastoma subgroups and subtypes using published gene expression data." (PMID 32720471, 2020). "In vivo experiments, preferably patient‐derived xenograft mouse models should clarify the relationship between REST depletion and tumorigenesis in medulloblastoma with the context of the microenvironment." (PMID 32720471, 2020).
medulloblastoma (continued). "We clustered the samples according to the proposed 12 medulloblastoma subtypes in order to demonstrate the expression differences of REST between and within the subtypes." (PMID 32720471, 2020). "We sought to identify the contribution of REST in the medulloblastoma cell line (Daoy) proliferation." (PMID 32720471, 2020). "In this study, we applied the in silico analysis to explore differences in REST expression between the medulloblastoma subgroups using the publicly available gene expression dataset [GSE85217]." (PMID 32720471, 2020). "Approximately 80% of medulloblastoma tissue samples have been reported to display an elevated repressor element 1‐silencing transcription factor (REST) expression which is concomitant with poor cellular differentiation." (PMID 32720471, 2020). "Additional drugs, active against various cancers, were inhibitors of the epigenetic function of REST, affecting the viability of medulloblastoma cells." (PMID 31905747, 2019). "In the medulloblastomas of Reference 47, the REST-mSin3 cooperation, important for the effects of the factor, was prevented by drugs that, however, are still under investigation." (PMID 31905747, 2019). "An additional study of medulloblastoma revealing the chromatin compaction induced by REST via Akt activation identified a new potential subgroup of specific therapeutic targets." (PMID 31905747, 2019). "Blockers of an epigenetic complex including USP37 and REST are considered as anti-medulloblastoma factors." (PMID 31905747, 2019). "Previous work from our group and others has shown that REST is important for medulloblastoma progression and maintenance." (PMID 29435175, 2018). "Accordingly, many human medulloblastoma tumors show significantly higher REST protein levels than adjacent normal brain tissue." (PMID 23216891, 2012). "In neoplasia, heightened REST function in medulloblastoma tumor cells contributes to their tumorigenicity in mouse models of the disease, in part by preventing their differentiation." (PMID 23216891, 2012). "Moreover, elevated levels of lysine-specific demethylase 1 (LSD1) and REST are observed in medulloblastoma, which promotes medulloblastoma cell migration." (PMID 40006989, 2025). "LSD1 inhibition of REST blocks the REST-dependent cell migration of medulloblastoma cells." (PMID 40006989, 2025). "Collectively, these findings shed light on the crucial role of REST in medulloblastoma." (PMID 40006989, 2025). "VEGFR-1 allows vascular growth and also displays molecular and functional features of endothelial cells, suggesting that REST may alter cell fate decisions in medulloblastomas by modulating the expression of transcription factors that control angiogenesis." (PMID 40006989, 2025). "Abnormal expression of REST regulates neurogenesis and is observed in the case of medulloblastoma." (PMID 40006989, 2025). "In addition, REST mediates cancer progression in medulloblastoma by chromatin remodeling, epigenetic repression of the genes that encode PTCH1 and PTEN, thereby enhancing proliferative and migratory signaling by sonic hedgehog (SHH) and AKT activation." (PMID 40006989, 2025). "Thus, our study is one of the first to connect VHL to REST-dependent control of autophagy in a subset of medulloblastomas." (PMID 38866867, 2024). "Elevated REST expression in medulloblastoma tumors has been reported in several studies; however, it is unclear whether all medulloblastoma subgroups and subtypes display an elevated REST expression." (PMID 32720471, 2020). "In this study, we sought to investigate the function of REST in the Daoy medulloblastoma cell line in order to determine whether REST repression is required for HDACi anti‐cancer effects." (PMID 32720471, 2020). "Moreover, various drugs induced inhibition of medulloblastomas by competing for the interaction of REST with its co-repressor mSin3." (PMID 31905747, 2019).
medulloblastoma (continued). "Although in non-HD models, lithium downregulated REST binding and protein levels in a rat fetal alcohol syndrome model whereas valproate upregulated REST transcription in medulloblastoma cells but neuroprotectively repressed REST in the Niemann-Pick Type C disease NPC1 knockout mouse." (PMID 24248060, 2013). "Additionally, inhibiting REST via LSD1 inhibition inhibited medulloblastoma migration." (PMID 37892159, 2023). "It should be noted that the conclusion of our study was derived from one experimental cell line which represents the SHH medulloblastoma subtype, hence it is not known whether other cell models would show comparable response to REST deficiency." (PMID 32720471, 2020). "Our previous studies showed that REST enhances cell proliferation, metastasis and vascular growth and blocks neuronal differentiation to drive progression of SHH medulloblastoma tumors." (PMID 38866867, 2024). "Expression of REST, a negative regulator of neurogenesis, is aberrantly elevated in SHH medulloblastomas and contributes to tumor progression through upregulation of hedgehog signaling and cell proliferative pathways." (PMID 33469989, 2021). "The expression of REST was modulated using a CRISPR/Cas9‐based knockout and a small hairpin (sh)RNA knockdown approach in human medulloblastoma Daoy cell lines." (PMID 32720471, 2020). "Further, the expression of REST was modulated using the CRISPR/Cas9 knockout and shRNA knockdown in the Daoy medulloblastoma cell line." (PMID 32720471, 2020). "The analysis revealed a wide variation in REST expression between the medulloblastoma subgroups, in particular, with the SHH subgroup and these findings are in line with the known medulloblastoma heterogeneity." (PMID 32720471, 2020). "Increase of deubiquitinase was found to reduce the expression of REST target genes (examples: TUBB3, SYN1, and SCG10), with decreased proliferation of medulloblastoma cells." (PMID 31905747, 2019). "The transient expression of a competitive form of REST, REST-VP16, inhibited medulloblastoma." (PMID 37892159, 2023). "In addition, the REST expression is closely related to the depth of malignant tumor invasion, TNM stage, and local lymph node metastasis, and the patients with high REST expression had a worse overall survival in medulloblastoma." (PMID 33834072, 2021). "This conclusion is further supported by the findings of several of microarray and next‐generation sequencing gene expression studies that were performed using primary human medulloblastoma; however, the findings of these studies did not suggest REST as a factor in sustaining the tumor cell growth." (PMID 32720471, 2020). "High REST expression has been reported as a negative prognostic factor for survival in GBM and medulloblastoma patients." (PMID 38711090, 2024).
glioblastoma (21 papers, 2009 to 2025). The most malignant astrocytic tumor (WHO grade IV). "Overall, these results establish that glioblastoma cells can compensate for the loss of REST required for their growth via upregulation of fatty acid metabolism, specifically, upregulation of ACSL enzymes, which can be blocked with Triacsin C." (PMID 38609948, 2024). "We developed a new optimized chemical lead (GR-28) that causes degradation of REST protein in REST-dependent glioblastoma cells via covalent inhibition of SCP1." (PMID 38609948, 2024). "Our results corroborated published reports: REST loss led to slower migration of glioblastoma cells, as was estimated by wound scratch assay." (PMID 38609948, 2024). "Dysregulated REST activity has been implicated in various diseases, among which the most deadly is glioblastoma multiforme (GBM)." (PMID 27698411, 2016). "Furthermore, gene expression of four tested GSC markers (CD133, SOX11, ALDH1A3, S100A4) was markedly reduced upon REST loss compared with wild-type glioblastoma cells." (PMID 38609948, 2024). "Other reports have implicated REST in the control of glioblastoma cell migration." (PMID 29435175, 2018). "The diverse functional modules enriched in the REST associated transcripts implied that REST may coordinate with these modules to initiate and promote glioblastoma." (PMID 27698411, 2016). "The CRISPR/Cas9 knockout of the REST gene revealed the role of REST in the proliferation of glioblastoma." (PMID 40006989, 2025). "We demonstrated that REST is a driver of glioblastoma proliferation using CRISPR/Cas9 knockout, with genetic analysis also highlighting its critical role in GBM cell migration and stemness maintenance." (PMID 38609948, 2024). "Unlike in non-neural HEK293 cells, downregulated genes common in T98G REST-KO clones formed several significant gene ontology (GO) categories, highlighting tissue-specific functions of REST in glioblastoma (lower)." (PMID 38609948, 2024). "Remarkably, our results revealed that combinatorial REST targeting using GR-28 and the fatty acid pathway inhibitor Triacsin C led to synergistic cell death in glioblastoma cells with high basal REST levels." (PMID 38609948, 2024). "Specifically, glioblastomas with a high-REST tumor subpopulation can be potentially diagnosed and then targeted with selective REST inhibitors alone or combined with other chemotherapeutic agents." (PMID 38609948, 2024). "In this study, we started with a well-characterized high-REST glioblastoma cell line (T98G) to validate the role of REST in glioblastoma growth." (PMID 38609948, 2024). "In this study, we utilized a combination of genetic and cellular approaches to demonstrate that REST significantly promotes glioblastoma proliferation, as well as plays an important role in GBM cell migration and self-renewal." (PMID 38609948, 2024). "Chronologically, one of the initial studies on REST in glioblastoma stem cells (GSC) demonstrated that GSC with high REST expression produced more invasive tumors compared to those with low REST expression in orthotopic mouse tumor models." (PMID 38609948, 2024). "We developed new small molecule inhibitory compounds targeting small C-terminal domain phosphatase 1 (SCP1) to reduce REST protein level and transcriptional activity in glioblastoma cells." (PMID 38609948, 2024). "Due to its crucial function in the repression of neuronal differentiation, REST protein stabilization is critical for maintaining pluripotency in glioblastoma CSCs." (PMID 34638302, 2021). "Our genomic characterization of REST for the first time revealed global transcriptomic deregulations in glioblastoma." (PMID 27698411, 2016).